TYK2 (tyrosine kinase 2)
Diseases named in the same sentence as TYK2 in open-access papers (continued):
Sharing a sentence is not in itself a finding about the gene and the disease.
B-cell lymphoma (1 paper, 2018). "The combination of a rare type of EBV-associated B-cell lymphoma with severe T-cell lymphopenia associated with compound heterozygous TYK2 mutations represents a distinct disease entity." (PMID 29725107, 2018). "Nevertheless, further investigations are required for verifying an alternative possibility that unknown other genetic mutations might be associated with aggressive development of EBV-associated B-cell lymphoma under low TYK2 activity." (PMID 29725107, 2018). "Herein, we report a recessive partial TYK2 deficiency in two siblings who presented with T-cell lymphopenia characterized by low naïve CD4+ T-cell counts and who developed Epstein-Barr virus (EBV)-associated B-cell lymphoma." (PMID 29725107, 2018).
brain tumours (1 paper, 2008). "The induction of growth arrest and apoptosis by PPARγ agonists was associated with the expression of PPARγ and inhibition of Tyk2-Stat3 signalling pathway in BTSCs, further suggesting the use of PPARγ agonists in the treatment of brain tumours." (PMID 19018263, 2008).
breast tumor (1 paper, 2026). "TYK2 blockade promotes metastasis in breast tumor cell- and patient-derived xenografts." (PMID 41882003, 2026).
C. perfringens infection (1 paper, 2023). "On day 19, coccidia and C. perfringens infection significantly up-regulated mRNA levels of TYK2 and TAK1 (p < 0.05)." (PMID 38136901, 2023).
carcinoid (1 paper, 2025). "Finally, we confirmed significantly reduced cell viability in the carcinoid cell line H727 following siRNA of tyrosine kinase 2 which is specifically upregulated in carcinoid NET." (PMID 39995112, 2025).
Chagas disease (1 paper, 2018). A parasitic infection caused by Trypanosoma cruzi. "Our results suggest that TYK2 does not seem to play an important role neither in the predisposition nor in the progression of an infectious condition like Chagas disease." (PMID 29304122, 2018). "Therefore, according to our results, TYK2 gene variants do not seem to play an important role in Chagas disease susceptibility and/or chronic Chagas cardiomyopathy." (PMID 29304122, 2018).
Chronic colitis (1 paper, 2022). A chronic inflammatory disease of the large intestine (colon, cecum and rectum). "To investigate whether deletion of Tyk2 in epithelial cells has an impact on the severity of chronic colitis, we monitored the body weights of Tyk2fl/fl and Tyk2ΔIEC mice during the course of AOM-DSS treatment." (PMID 36185806, 2022).
chronic mucocutaneous candidiasis (1 paper, 2022). "Patient P-Jap was the only TYK2-deficient patient reported to suffer from chronic mucocutaneous candidiasis, which was attributed to impaired IL-12 and IL-23 responses and defective Th17 immunity, as seen in patients with IL-12Rβ1 deficiency." (PMID 36094518, 2022).
chronic myeloid leukemia (1 paper, 2020). "Moreover, in chronic myeloid leukemia blast cells, the long noncoding RNA MEG3 interacted with multiple proteins in a large complex comprising DNMT1, JAK2, TYK2, STAT3, and HDAC155." (PMID 32895373, 2020).
colorectal adenocarcinoma (1 paper, 2024). The most common type of colorectal carcinoma. "Semi-quantitative immunoblot analysis revealed that the protein level of TYK2 was significantly higher in healthy controls than in matched colorectal adenocarcinomas." (PMID 39518103, 2024). "In this study, we show for the first time that the expression level of TYK2 in colorectal adenocarcinomas significantly differs from that in normal colonic mucosa samples that has diagnostic value and is associated with clinicopathological data." (PMID 39518103, 2024).
colorectal polyps (1 paper, 2026).
colorectal tumors (1 paper, 2026). "This indicates that TYK2 also mediates immunosurveillance of primary transplanted colorectal tumors but, unlike CRLM, is not specifically required in DCs." (PMID 40991399, 2026).
cutaneous candidiasis (1 paper, 2024). Candidiasis of the skin manifested as eczema-like lesions of the interdigital spaces, perleche, or chronic paronychia. "Taken together, our study unravels a novel and as yet unrecognized detrimental role of TYK2 and IFNγ signaling in the immune defense against invasive cutaneous candidiasis and paves the way for exploring TYK2 inhibitors as potential treatment option." (PMID 39622833, 2024). "In the present work, we analyzed the role of TYK2 in the immune response against cutaneous candidiasis using gene-targeted mouse models, including complete and conditional Tyk2 knockout mice as well as mice expressing a kinase-inactive version of TYK2." (PMID 39622833, 2024). "Another key finding of our study is that Tyk2-/- and Tyk2K923E mice show a similar reduction in C. albicans invasion into the deep skin and dissemination to kidneys when compared to wild-type controls, suggesting that TYK2 kinase inhibition might be an option to treat cutaneous candidiasis." (PMID 39622833, 2024). "Here, the authors show that absence of tyrosine kinase 2 protects from invasive cutaneous candidiasis." (PMID 39622833, 2024).
deep vein thrombosis (1 paper, 2026). "Unlike JAK inhibitors, TYK2 inhibitors do not carry the same risk of venous thromboembolism or major adverse cardiovascular events, which informed our decision to pursue this therapy for a patient with a remote history of deep vein thrombosis." (PMID 41446689, 2026).
esophageal cancer (1 paper, 2022). A primary or metastatic malignant neoplasm involving the esophagus. "In addition, the inhibition of TYK2 reduces the aggressiveness of breast and esophageal cancer cells." (PMID 36531252, 2022).
fibrosarcoma (1 paper, 2022). A malignant mesenchymal fibroblastic neoplasm affecting the soft tissue and bone. "Like P1104A, all the missense proteins resulted in impaired responses to IL-23 in TYK2-deficient fibrosarcoma (U1A) cells stably expressing IL-12Rβ1 and IL-23R." (PMID 36094518, 2022).
Flavivirus Infections (1 paper, 2010). Infections with viruses of the genus FLAVIVIRUS, family FLAVIVIRIDAE. "WNV nonstructural proteins inhibit IFN-α/β signaling by preventing JAK1 and Tyk2 phosphorylation and IFN-β gene transcription, therefore the antiviral effects mediated by IFN during flavivirus infection primarily benefit uninfected cells in the vicinity of infected cells." (PMID 20661470, 2010).
gestational diabetes (1 paper, 2024). Carbohydrate intolerance first diagnosed during pregnancy. "Differing from T1DM, neither study up to this current research has identified a connection between variants of TYK2 and COL4A3 genes and the likelihood of developing gestational diabetes." (PMID 38926794, 2024).
glioma (1 paper, 2023). A benign or malignant brain and spinal cord tumor that arises from glial cells (astrocytes, oligodendrocytes, ependymal cells). "The survival and expression level have no obvious correlation in glioma patient with or without TYK2 expression level." (PMID 37416766, 2023).
graft versus host disease (1 paper, 2023). An immune system disorder that occurs after allogeneic hematopoietic stem cell transplant and is a reaction of donor immune cells against host tissues. "Ruxolitinib, an approved drug that targets TYK2, is a kinase inhibitor used to treat patients with myelofibrosis and polycythemia vera who have not responded to or are unable to tolerate the use of hydroxyurea, and to treat graft-versus-host disease when steroid treatments have failed." (PMID 37886583, 2023).
granuloma annulare (1 paper, 2025). Granuloma annulare is a long-term (chronic) skin disease consisting of a rash with reddish bumps arranged in a circle or ring. "Prospective evaluation will be essential to determine the role of TYK2 inhibition in the long-term management of granuloma annulare and to establish its place among available therapeutic options." (PMID 41523549, 2025).
Hepatic fibrosis (1 paper, 2022). The presence of excessive fibrous connective tissue in the liver. "IPA of MYOC/CCL19 fibroblast gene expression correlating with the mRSS revealed several prominent pathways: senescence, hepatic fibrosis signaling, IL-6 signaling, STAT3 signaling, TGF-β signaling, protein ubiquitination, JAK/Stat signaling, and role of JAK1, JAK2 and TYK2 in interferon signaling." (PMID 35943798, 2022).
hepatitis C infection (1 paper, 2018). "Suppression and impairment of anti-viral activity of interferon α (IFNα) has been shown in hepatitis C infection through inhibition of Jak1/Tyk2/STAT1 phosphorylation and upregulation of PP2A dependent upon NS5A protein." (PMID 29447178, 2018).
hidradenitis suppurativa (1 paper, 2025). A chronic suppurative and cicatricial disease of the apocrine glands occurring chiefly in the axillae in women and in the groin and anal regions in men. "TYK2/PDE4 inhibitors demonstrated significantly inferior efficacy versus IL-17 blockers, with unproven efficacy in hidradenitis suppurativa." (PMID 41142781, 2025).
inflammatory skin disease (1 paper, 2020). Inflammatory skin disorders covers a broad category that includes many conditions ranging in severity, from mild itching to grave medical health complications These disorders are common in people of all ages and races. "It has further been reported that nonspecific TYK2 inhibitors are effective at blocking IL-23–mediated inflammatory skin disease, in line with in vivo reports in TYK2-deficient mice." (PMID 32149730, 2020).
invasive carcinoma (1 paper, 2022). A carcinoma that is not confined to the epithelium, and has spread to the surrounding stroma. "Combined Tyk2 deletion in cancer cells and cells of the tumor stroma promotes CRC progression to invasive carcinomas." (PMID 36185806, 2022).
lung adenocarcinoma (1 paper, 2014). A carcinoma that arises from the lung and is characterized by the presence of malignant glandular epithelial cells. "When we tested the impact of SIAH2 on the TK TYK2, we found that ectopic expression of SIAH2 in human embryonic kidney cells (293T cells) and in human lung adenocarcinoma H1299 cells strongly decreased the levels of TYK2." (PMID 24833526, 2014).
lupus erythematosus (1 paper, 2024). An autoimmune, connective tissue chronic inflammatory disorder affecting the skin, joints, kidneys, lungs, heart, and the peripheral blood cells. "Recently, there has been promising data for TYK-2 inhibitors in the management of lupus erythematosus." (PMID 38883165, 2024).
lymph node metastasis (1 paper, 2020). "Therefore, JAK3/TYK2 level can impact the prognosis of STAD patients with lymph node metastasis." (PMID 33083484, 2020).
lymphopenia (1 paper, 2025). Reduction in the number of lymphocytes. "In our case, the immunological profile, featuring CD4+ lymphopenia and elevated IgE, corresponds to previously reported “hyper-IgE–like” phenotypes occasionally observed in TYK2 deficiency." (PMID 41465118, 2025).
male infertility (1 paper, 2022). The inability of the male to effect fertilization of an ovum after a specified period of unprotected intercourse. "In addition, members of the JAK-STAT pathway, TYK2, STAT1 and STAT4, have been shown to be active in human sperm, indicating that defects in the JAK-STAT pathway in sperm may be related to male infertility." (PMID 36003498, 2022).
myelitis (1 paper, 2021). An inflammatory process affecting the spinal cord. "In patient 18ZC026 (myelitis), we found the rs12720356 variant in the TYK2 gene." (PMID 33815474, 2021).
myeloproliferative diseases (1 paper, 2025). "Thus, in addition to JAK2 V617F, TYK2 V678F mutations may also contribute to the development of myeloproliferative disorders, including MDS." (PMID 40519492, 2025). "Given the emerging understanding of TYK2 as an oncogenic driver in myeloproliferative diseases, further studies are warranted to clarify the therapeutic implications of TYK2 inhibition in this patient population." (PMID 40519492, 2025). "Taken together, these findings suggest that TYK2 may function as a proliferative oncogenic driver in myeloproliferative disorders, including MDS." (PMID 40519492, 2025). "Recent studies have highlighted TYK2 as a potential oncogenic driver in myeloproliferative disorders, suggesting that TYK2 inhibition is unlikely to exacerbate diseases such as MDS." (PMID 40519492, 2025). "However, our understanding of TYK2's role as an oncogenic kinase is still in its early stages, and both basic research and clinical data on its relevance to MDS and other myeloproliferative neoplasms remain limited." (PMID 40519492, 2025).
nasopharyngeal carcinoma (1 paper, 2025). A carcinoma arising from the nasopharyngeal epithelium. "For instance, in nasopharyngeal carcinoma, TRIM21-mediated K48-linked ubiquitination promotes the degradation of LHPP and then downregulates TYK2-STAT1phosphorylation to inhibit the progression of nasopharyngeal carcinoma." (PMID 40379610, 2025).
pancreatic adenocarcinoma (1 paper, 2022). "However, TYK2 expression was decreased in Pancreatic adenocarcinoma (PAAD)." (PMID 36531252, 2022).
peripheral T-cell lymphomas (1 paper, 2019). "Among peripheral T-cell lymphomas ALCL has been associated with the highest level of IL-10 expression, and ALCL cells also express the IL-10 receptor, which provides an autocrine mechanism for the aberrant activation of TYK2 in ALCL cells." (PMID 30131584, 2019).
pityriasis rosea (1 paper, 2024). A mild, self-limited skin disorder that is most commonly seen in children and young adults. "However, the recognition of a pityriasis rosea-like drug eruption in the context of TYK2 inhibition, coupled with previous reports associated with tyrosine kinase inhibitors and adalimumab, highlights the complex interplay between immune modulation and cutaneous manifestations." (PMID 39430635, 2024).
pulmonary TB (1 paper, 2016). "Therefore, TYK2 may involve in the pathogenesis of pulmonary TB via regulating IL-10." (PMID 27655333, 2016).
Salmonella Infections (1 paper, 2018). Infections with bacteria of the genus SALMONELLA. "Indeed, BCG and Salmonella infections that are likely due to impaired IL-12 responses have been previously observed in TYK2-deficient patients." (PMID 29725107, 2018).
severe combined immunodeficiency (1 paper, 2018). Severe combined immunodeficiency (SCID) comprises a group of rare monogenic primary immunodeficiency disorders characterized by a lack of functional peripheral T lymphocytes resulting in early-onset severe respiratory infections and failure to thrive. "For example, mutant Jak1 and Jak3 mice have severe combined immunodeficiency (SCID), and Jak1 mutants also have neurological defects and poor survival past birth; knock out mutations in Jak2 are embryonic lethal, and mutations in the Jak family member Tyk2 result in poor response to pathogens." (PMID 30558204, 2018).
tauopathy (1 paper, 2024). Neurodegenerative disorders involving deposition of abnormal tau protein isoforms (tau proteins) in neurons and glial cells in the brain. "Partial reduction of Tyk2 postnatally reverses tau-associated pathological phenotypes in two different tauopathy mouse models." (PMID 39528671, 2024). "Notably, we show that knockdown of Tyk2 in the P301S transgenic mouse model of tauopathy reduces pathogenic, hyperphosphorylated tau as well as total amounts of tau protein." (PMID 39528671, 2024). "Furthermore, knockdown of Tyk2 reduced total tau and pathogenic tau levels and rescued gliosis in a tauopathy mouse model." (PMID 39528671, 2024). "Nevertheless, Y29 phosphorylation by TYK2 promotes the accumulation of pathological tau species in a virally induced tauopathy mouse model." (PMID 39528671, 2024).
Thrombocytosis (1 paper, 2024). Increased numbers of platelets in the peripheral blood. "Tofacitinib-thrombocytosis was the only drug-ADR pair that was significant in all KOBIO, FAERS, and CDM results, and tofacitinib is a well-known drug that targets JAK 1,2,3 and TYK2." (PMID 38302579, 2024).
trisomy 21 (1 paper, 2016). A chromosomal disorder consisting of the presence of an extra chromosome 21. "An shRNA screen determined that the interferon-activated kinases JAK1 and TYK2 suppress proliferation of trisomy 21 fibroblasts, and this defect is rescued by pharmacological JAK inhibition." (PMID 27472900, 2016).
vasculitis (1 paper, 2024). "Tyrosine kinase 2 (TYK2) polymorphisms (rs2304256C > A, rs280519A > G, and rs12720270G > A) may be potential protective factors against anti-neutrophil cytoplasmic antibody (ANCA)-associated vasculitis (AAV)." (PMID 39726748, 2024).
viral hepatitis (1 paper, 2023). An acute or chronic inflammation of the liver parenchyma caused by viruses. "Taken together, RBV, starting with the upregulation of TYK-2, interferes with the IL-12 cascade and ultimately leads to an increased IFN-γ production, which has shown to be crucial in the immune response to viral hepatitis." (PMID 36766795, 2023).